PIK3CA (phosphatidylinositol-4,5-bisphosphate 3-kinase catalytic subunit alpha)
Diseases named in the same sentence as PIK3CA in open-access papers (continued):
Sharing a sentence is not in itself a finding about the gene and the disease.
endometrioid ovarian cancers (14 papers, 2015 to 2025). "Combination of inactivation of ARID1A with activation of PIK3CA activates the development of ovarian endometrioid carcinoma." (PMID 35070505, 2022). "A maximum of six mutations was present in one patient with endometrioid ovarian carcinoma (MSH6, PIK3CA, FBXW7, PIK3R1, PITCH1, ERBB3 and PPP2R1A)." (PMID 32120793, 2020). "Activation of the PI3K/AKT pathway (through mutation of PIK3CA and AKT or inactivating mutations of PTEN) is a frequent event in clear-cell and endometrioid ovarian cancers." (PMID 26413541, 2015). "Activation of oncogenic KRAS and PIK3CA pathways and inactivation of tumor suppressor genes, ARID1A and PTEN, are observed in clear cell and endometrioid ovarian carcinomas, respectively." (PMID 34454550, 2021).
mucinous carcinoma (14 papers, 2013 to 2024). "FC PIK3ca* mice rapidly develop moderately invasive mucinous adenocarcinomas." (PMID 23593290, 2013).
nasopharyngeal carcinoma (14 papers, 2013 to 2025). A carcinoma arising from the nasopharyngeal epithelium. "In nasopharyngeal carcinoma, PIK3CA amplification was strongly associated with distant metastasis, lymph node involvement, advanced tumor stage, and ultimately with reduced overall survival." (PMID 27095573, 2016). "In nasopharyngeal carcinoma cell-derived EVs, the secretion of PIK3CA was evidenced and phosphorylates PIP2 as the first step of PI3K-Akt signaling pathway." (PMID 34186243, 2021). "First, it moderately downregulated the p110α level, leading to a slight reduction in the P-AKT level, which is in line with a previous study on nasopharyngeal carcinoma showing that Sox2 can activate AKT by inducing the transcription of the PIK3CA gene." (PMID 33228022, 2020). "We modeled the development of acquired resistance in patients by treating PIK3CA mutant nasopharyngeal carcinoma cells (CNE2, HONE1) with increasing doses of BEZ235 for 6 to 9 months to select BEZ235-resistant sublines (CNE2/235, HONE1/235)." (PMID 25762617, 2015). "PIK3CA alteration has also been reported in nasopharyngeal carcinoma." (PMID 39409902, 2024). "Similarly, SOX2 and KLF4 jointly drive PIK3CA expression in nasopharyngeal carcinoma, thus enhancing PI3K/AKT activity and tumorigenesis, while overexpression of PI3KCA rescues growth inhibitory effects imposed by SOX2 knock-down." (PMID 31477842, 2020). "The results of their network analysis experiments showed that the anti-nasopharyngeal carcinoma effect of CEP was related to eight core targets such as EGFR, AKT1, PIK3CA and mTOR." (PMID 41368570, 2025). "To further validate that SOX2 upregulates PIK3CA expression thereby activating PI3K/Akt signaling pathways in nasopharyngeal carcinoma, we overexpressed PIK3CA in HNE-1 nasopharyngeal carcinoma cells with SOX2 shRNAs or a control shRNA." (PMID 30108202, 2018). "Activation of the PI3K pathway, generally as a result of PIK3CA amplification, has been reported in upper aerodigestive tract cancers including 12% of lung squamous cell carcinoma (SCC), 18.2% of nasopharyngeal carcinoma, 20% of oropharyngeal SCC, and 32.2% of HNSCC." (PMID 27095573, 2016).
uterine cancer (14 papers, 2011 to 2025). Primary or metastatic malignant neoplasm involving the uterine corpus and/or the cervix. "We find that oncogenic PIK3CA mutations, common in spontaneously arising estrogen-associated de novo uterine cancer, are significantly less frequent in tamoxifen-associated tumors." (PMID 40846762, 2025). "In this retrospective study, the most frequent genetic alterations occurred in PIK3CA (32.6%) among patients with high-risk postoperative uterine cancer." (PMID 34012039, 2021). "The AUPR was high in cancer types with high PIK3CA mutation rates such as colon, breast and uterus cancer types." (PMID 33166334, 2020). "Similarly, a study in PIK3CA positive primary uterine carcinomas cells, demonstrated a stronger growth inhibition by taselisib, when compared with WT cells, as well as in vivo tumor growth inhibition in mice with PIK3CA mutation." (PMID 36523963, 2022). "The same pattern was also observed in uterine cancers with ARID1A mutations, which were enriched in a series of 222 cases of uterine cancer with PIK3CA and PTEN mutations." (PMID 34659566, 2021). "Thus, detection of co-mutations of both PIK3CA and PTEN may offer potential biomarkers or targets for individualized treatment of tumors in uterine cancer or other cancer types." (PMID 32101536, 2020).
Klippel-Trenaunay syndrome (13 papers, 2015 to 2025). "PIK3CA variants were found in 67% of Klippel Trenaunay Syndrome individuals; KRAS variants in 60% of arteriovenous malformations; MET was mutated in 75% of lymphovenous malformations." (PMID 35807022, 2022). "Similar to CLOVES, Klippel-Trenaunay syndrome (KTS) is due to somatic mutations in PIK3CA, becoming its most relevant differential diagnosis." (PMID 35096710, 2021). "A biopsy, coupled to a blood sample, can also be used for molecular biology analyses, to search for activating mutations of the PIK3CA gene, particularly with LM integrating in a syndromic form (CLOVES or Klippel-Trenaunay syndrome) but also in certain isolated (or common) LMs." (PMID 36639640, 2023). "A biopsy (coupled to a blood sample) can also be used for molecular biology analyses, to search for activating mutations of the PIK3CA gene, particularly with LM integrating in a syndromic form (CLOVES or Klippel-Trenaunay syndrome) but also in certain isolated LMs." (PMID 36639640, 2023). "It has been shown that 19 of 21 individuals with Klippel-Trenaunay syndrome (KTS), 5 of 8 with fibro-adipose vascular anomaly (FAVA), and 31 of 33 with congenital lipomatous overgrowth with vascular, epidermal and skeletal anomalies (CLOVES) were mosaic for specific PIK3CA mutations." (PMID 29985963, 2018).
megalencephaly-capillary malformation (13 papers, 2015 to 2023). "Somatic mutations in PIK3CA account for about 90% of the Megalencephaly-capillary malformation syndrome (MCAP) cases reported so far, including subjects initially described as macrocephaly-cutis marmorata telangiectatica congenital syndrome." (PMID 35096710, 2021).
metastatic carcinoma (13 papers, 2012 to 2025). A carcinoma which has spread from the original site of growth to another anatomic site. "Here we describe extraordinary and life-threatening reactions beyond skin rash in two patients with progressive PIK3CA-mutated metastatic cancer in whom alpelisib was initiated." (PMID 37086483, 2023). "This article describes extraordinary and life-threatening reactions beyond skin rash in two patients with progressive PIK3CA-mutated metastatic cancer." (PMID 37086483, 2023). "In various metastatic cancers, patients treated with PI3K/AKT/mTOR pathway inhibitors in combination with other treatments (ET, anti-HER2 therapy, or chemotherapy) had a longer time to progression compared to patients without PIK3CA mutations." (PMID 38413796, 2024).
Obesity (13 papers, 2016 to 2025). Accumulation of substantial excess body fat. "Increased TILs, higher TMB, obesity, and uncontrolled blood glucose levels were associated with a decreased risk of progression, whereas tumor HLA-A expression, PIK3CA variants, and the LAR subtype were associated with a greater risk of progression for patients receiving the combination." (PMID 38095878, 2024). "PIK3CA mutation (hazard ratio (HR): 0.61; 95% confidence interval (CI): 0.37–0.99; P=0.046), overweight (HR: 0.56; 95% CI: 0.32–0.96; P=0.033) and obesity (HR: 0.44; 95% CI: 0.20–0.95; P=0.036) were associated with a significantly lower cumulative complete response (CR) rate." (PMID 38023131, 2023). "Moreover, accumulation of DNA mutations, such as APC, KRAS, NRAS, BRAF, or PIK3CA, makes obesity a multifactor phenomenon involved in CRC initiation and progression." (PMID 36235624, 2022). "The frequency of KRAS and PIK3CA mutations were significantly decreased in obesity group." (PMID 33197880, 2020). "Our study suggests that obesity may be one factor that influences AKT signaling downstream of an activating PIK3CA mutation." (PMID 29423104, 2018). "Moreover, accumulation of DNA mutations, as in APC, KRAS, NRAS, BRAF, or PIK3CA, and insulin secretion sets obesity as a multifactor phenomenon involved in CRC initiation and aggressive development." (PMID 26801617, 2016). "In summary, we demonstrated the gene mutation frequency (especial in PIK3CA and KRAS), as well as CNV of obesity groups, were decreased." (PMID 33197880, 2020). "Large prospective cohorts should examine interactions between obesity-related genetic polymorphisms (e.g., CYP19A1, PTEN, PIK3CA), adipokine expression profiles, and metabolomic signatures to delineate high-risk phenotypes requiring intensified preventive surveillance." (PMID 41301707, 2025). "Interestingly, more co-occurrences between mutations were demonstrated in obesity group compared with normal group (APC and KRAS, PIK3CA and KRAS, etc.)Finally, we investigated the copy number variation (CNV) in two group." (PMID 33197880, 2020). "The intersection of the results from these two plugins revealed that PIK3R1, PIK3CB, SRC, PIK3CA and PIK3 CD are core targets for the combined treatment of obesity via Crataegus pinnatifida andgut microbiota." (PMID 41032481, 2025). "In the present study, network pharmacology results showed that Crataegus pinnatifida combined with the obesity-related gut microbiota may treat obesity by targeting PIK3R1, PIK3CB, SRC, PIK3CA, PIK3 CD." (PMID 41032481, 2025). "Through network pharmacology analysis, we revealed that SMs of Crataegus pinnatifida and obesity-related gut microbiota could target obesity by interacting with PIK3R1, PIK3CB, SRC, PIK3CA and PIK3 CD." (PMID 41032481, 2025).
osteosarcoma (13 papers, 2015 to 2025). A usually aggressive malignant bone-forming mesenchymal neoplasm, predominantly affecting adolescents and young adults. "PIK3CA mutations, common in Class I, disrupt signaling pathways, contributing to osteosarcoma." (PMID 38800967, 2024). "Additional predicted targets of miR-30a and miR-30e within this pathway include PIK3CA, mTOR, FOXO3, MMP13, SOX9, BCL2, VEGFA, and CCND1, all of which have been previously associated with osteosarcoma pathogenesis." (PMID 40862758, 2025). "The SNP rs7646409 in PIK3CA intron triggers p110a overexpression, activating Akt signaling, suppressing osteosarcoma apoptosis, and promoting proliferation." (PMID 38800967, 2024). "In preclinical studies, BYL719 was shown to have anti-tumor activity in many cancer cell types namely nasopharyngeal, head and neck and osteosarcoma cells and recent evidence suggested PIK3CA mutant cells to be more sensitive to BYL719." (PMID 27602501, 2016). "Heuristic analysis of whole genome, exome, and RNA sequencing data from 59 osteosarcoma tumors revealed alterations in the PI3K/mTOR pathway in 24% of samples that included aberrations ofPTEN,TSC2, PIK3R1, PIK3CA, and several other genes." (PMID 27441088, 2016).
acute myeloid leukemia (12 papers, 2019 to 2025). Acute myeloid leukemia (AML) is a group of neoplasms arising from precursor cells committed to the myeloid cell-line differentiation. "PIK3CA followed as the second most commonly mutated gene, observed frequently across most cancer types except ovarian serous carcinoma (OV), kidney renal clear cell carcinoma (KIRC), lung adenocarcinoma (LUAD), and acute myeloid leukemia (AML)." (PMID 38920700, 2024).
anaplastic thyroid cancers (12 papers, 2010 to 2025). "In anaplastic thyroid cancers with well differentiated components, the PIK3CA mutations are restricted to the anaplastic component." (PMID 21048836, 2010). "BRAF and PIK3CA mutations cooperatively promoted anaplastic thyroid cancer." (PMID 31905960, 2019). "PTEN and PIK3CA mutations as well as PIK3CA copy gains rarely coexist in FTCs, while PI3K-PTEN-AKT pathway is common in poorly differentiated and anaplastic thyroid carcinomas, suggesting their important role in tumor progression." (PMID 33922518, 2021). "Somatic mutations of the catalytic subunit of the phosphatidylinositol 3′-kinase (PIK3CA) have been identified in about 23 percent of anaplastic thyroid cancers." (PMID 21048836, 2010).
cholangiocarcinoma (12 papers, 2011 to 2026). A carcinoma that arises from the intrahepatic biliary tree (intrahepatic cholangiocarcinoma) or from the junction, or adjacent to the junction, of the right and left hepatic ducts (hilar cholangiocarcinoma). "A gain-of-function mutation in PIK3CA was linked to acquired resistance to FGFR2 inhibitors in a patient with intrahepatic cholangiocarcinoma, underscoring its role in disease progression and therapy resistance." (PMID 41300430, 2025). "Also, in FGFR2-driven cholangiocarcinoma, mutations in PIK3CA and PTEN frequently occurred upon acquired resistance to FGFRis28." (PMID 41361008, 2026). "Also, overexpression of an activated form of YAP together with a mutant form of phosphatidylinositol-4,5-bisphosphate 3-Kinase catalytic subunit alpha (PIK3CA) induced the development of HCC and cholangiocarcinomas in the mouse liver." (PMID 28877210, 2017).
epilepsy (12 papers, 2014 to 2025). A brain disorder characterized by episodes of abnormally increased neuronal discharge resulting in transient episodes of sensory or motor neurological dysfunction, or psychic dysfunction. "PIK3CA somatic mutations have also been linked with epilepsy that arises through PIK3CA mutation driven developmental birth defects." (PMID 31018529, 2019). "To begin to dissect the cell signaling mechanisms underlying Pik3ca-driven epilepsy, we conducted reverse phase protein array (RPPA) analysis to measure protein levels of a comprehensive panel of cell signaling molecules." (PMID 26633882, 2015). "Dramatic phenotypes resulted, faithfully modeling the entire spectrum of PIK3CA-associated human brain disorders including enlarged brain size, hydrocephalus, cortical dysplasia and epilepsy." (PMID 26633882, 2015). "Specifically, the PIK3CA H1047R variant has been associated with severe somatic or brain overgrowth phenotypes including focal cortical dysplasia with severe epilepsy, whereas the MTOR T1977I variant is associated with megalencephaly and polymicrogyria and overall less severe epilepsy." (PMID 37741456, 2023). "We have previously generated the first genetic mouse models of patient-related PIK3CA mutations that recapitulate brain overgrowth, cortical dysplasia, hydrocephalus, and epilepsy, with phenotypic severity dependent on the mutant allele and its time of activation." (PMID 34899181, 2021). "We conclude that Pik3ca overactivation is sufficient to cause epilepsy." (PMID 26633882, 2015). "Focal cortical dysplasia type II results from somatic brain mutations in mechanistic target of rapamycin pathway activators MTOR, AKT3, PIK3CA and RHEB and is a major cause of drug-resistant epilepsy." (PMID 34632383, 2021). "While elevated MTOR activity is known to be epileptogenic, our data suggest that alternate PI3K-AKT targets acutely regulate neuronal hyperactivation in PIK3CA-driven epilepsy." (PMID 34899181, 2021). "Our study establishes an important foundation to determine active pathway-driven cellular mechanisms in Pik3ca-related epilepsy." (PMID 34899181, 2021). "We acknowledge, however, that altered neuronal circuitry are likely contributors to chronic mechanisms driving Pik3ca-mediated epilepsy." (PMID 34899181, 2021). "We previously generated mice with activating mutations of Pik3ca, the catalytic subunit of the phosphoinositide 3-kinase (PI3K) enzyme, to model human brain overgrowth syndromes including megalencephaly and epilepsy." (PMID 31094678, 2019). "We have previously characterized mouse models recapitulating human PIK3CA-related brain overgrowth, epilepsy, dysplastic gyrification and hydrocephalus." (PMID 31094678, 2019). "Further our data indicate that Pik3ca-related epilepsy is dissociable from brain overgrowth and cortical dysplasia." (PMID 26633882, 2015). "We conclude that epilepsy in these models represents an active Pik3ca-driven process that can be restricted by dynamic modulation of PI3K pathway activity in dysmorphic brains." (PMID 26633882, 2015). "Proteomic analyses of cell signaling networks in megalencephalic cortical and hippocampal tissue at baseline and treated with PTZ and/or BKM120 provide insight into the mechanism of Pik3ca-dependent epilepsy." (PMID 26633882, 2015). "ENS arises from activating mutations in PIK3CA or AKT3, which drive hyperactivation of the PI3K-AKT–mTOR signaling axis, clinically manifesting as epidermal nevi, hemimegalencephaly, and drug-resistant epilepsy." (PMID 40979205, 2025). "Other disorders of cellular proliferation—including Sturge-Weber syndrome caused by mutations in GNAQ, NPRL3-related cortical malformations, and PIK3CA-related overgrowth syndromes—also present with epilepsy that seems responsive to “rapalogs” like sirolimus and everolimus." (PMID 35250833, 2022).